HAR1A (highly accelerated region 1A)
Diseases named in the same sentence as HAR1A in open-access papers (continued):
Sharing a sentence is not in itself a finding about the gene and the disease.
tumor (10 papers, 2017 to 2025). "HAR1A deficiency, in turn, stimulated tumor growth and metastasis by activating the ANXA2/p65 axis." (PMID 38688909, 2024). "However, The molecular mechanisms underlying the HAR1A’s tumor-suppressing functions are largely unclear." (PMID 38688909, 2024). "This appears to be in contrast with our prognostic findings and with other studies describing a tumour suppressive role for HAR1A." (PMID 39602392, 2024). "This study aimed to discover the molecular mechanisms underpinning HAR1A’s tumor-suppressing functions in NSCLC." (PMID 38688909, 2024). "HAR1A was shown to have a tumour suppressor role in oral cancer via interaction with Alpha Kinase-1 (ALPK1), and in non-small cell lung cancer via modulation of the Signal Transducers and Activator of Transcription 3 (STAT3) pathways." (PMID 39602392, 2024). "For this reason, we analyzed the expression of REST and HAR1A in primary GBM cells derived from the tumour core and from the invasive margin of the same patient (patient 28)." (PMID 39602392, 2024). "We found that paclitaxel treatment or HAR1A overexpression significantly decreased tumor volume and weight compared to the control group." (PMID 38688909, 2024). "A study using TCGA-based bioinformatics analysis and microarray analysis revealed that HAR1A is a tumor suppressor involved in tumor progression via EMT regulation and is negatively associated with prognosis." (PMID 37691031, 2023). "Overall, rescue experiments confirm that the STAT3 signaling pathway is responsible for the tumor-suppressing effects of lncRNA HAR1A in NSCLC." (PMID 35740511, 2022). "Given the in vitro results, we further verified the tumor-suppressing role of HAR1A in NSCLC by using a xenograft tumor model." (PMID 35740511, 2022). "The long non-coding RNA (lncRNA), HAR1A is emerging as a putative tumour suppressor." (PMID 39602392, 2024). "Since the oncogenic role of the NF-kB signaling pathway is well documented, it is biologically plausible to infer that HAR1A may exert tumor-suppressing functions by repressing the ANXA2/NF-kB axis." (PMID 38688909, 2024). "The tumor-suppressing role of HAR1A was verified in the mouse model." (PMID 35740511, 2022). "Collectively, these indicate that HAR1A plays a tumor-suppressive role in tumorigenesis." (PMID 35740511, 2022). "HAR1A functions as a tumor suppressor in NSCLC by regulating the STAT3 signaling pathway." (PMID 35740511, 2022). "We next investigated whether HAR1A regulated tumor metastasis using a tail vein injection model." (PMID 38688909, 2024). "However, overexpression of HAR1A seemed to lead to a decrease in tumor size." (PMID 35740511, 2022). "Conversely, relative to normal solid tissue samples, REST was upregulated in primary and recurrent tumour samples and HAR1A / HAR1B were downregulated in both primary and recurrent tumours." (PMID 39602392, 2024). "REST, HAR1A, and HAR1B were all differentially expressed between the tumour core and periphery samples." (PMID 39602392, 2024). "The results indicated that ectopic expression of HAR1A inhibited NSCLC cell proliferation in vitro and growth of NSCLC tumor xenograft and vice versa." (PMID 35740511, 2022). "IHC staining unveiled that overexpression of HAR1A reduced tumor cell proliferation, as shown by decreased MCM2 and PCNA positive tumor cells in lenti-HAR1A cell-derived tumors." (PMID 35740511, 2022). "LINC00900, MIR210HG, MIR22HG, PVT1, and SNHG18 expression increased, whereas HAR1A, LINC00641, SLC25A21-AS1, and SNAI3-AS1 expression decreased with tumor grade." (PMID 34288803, 2021). "Subsequent analyses demonstrated that the expressions of PVT1 and CYTOR were up-regulated, while HAR1A and MIAT were down-regulated in diffuse glioma samples compared to non-tumor tissues." (PMID 29108264, 2017).
tumor (continued). "Our results showed that the relative expression levels of CYTOR and PVT1 were up-regulated, while HAR1A and MIAT were significantly down-regulated in diffuse glioma specimens compared to non-tumor tissues (all P <0.001)." (PMID 29108264, 2017). "Furthermore, we confirmed that HAR1A and HAR1B expression is comparable intra-tumour cell lines derived from both the GBM core and clinically relevant invasive margin, the latter region reflective of residual disease post-surgery." (PMID 39602392, 2024). "Our data showed a significant up-regulation of REST, but not HAR1A in the invasive margin, relative to the tumour core." (PMID 39602392, 2024).
infection (1 paper, 2022). The state of being infected such as from the introduction of a foreign agent such as serum, vaccine, antigenic substance or organism. "Infection of LV-shHAR1A significantly reduced the expression level of lncRNA HAR1A in NCI-H1975 cells, whereas HAR1A expression was significantly elevated in LV-HAR1A infected A546 cells." (PMID 35740511, 2022).
HAR1A also shares sentences with these, for which no sentence is quoted: Alzheimer disease (1 paper); Auditory hallucination (1); autism spectrum disorder (1); breast invasive carcinoma (1); gastric cancer (1); oligoastrocytoma (1); oligodendroglioma (1); pancreatic cancer (1); papillary thyroid cancer (1); Parkinson disease (1); prostate adenocarcinoma (1).